LITAF (lipopolysaccharide induced TNF factor)
Diseases named in the same sentence as LITAF in open-access papers (continued):
Sharing a sentence is not in itself a finding about the gene and the disease.
autosomal dominant disease (1 paper, 2020). Autosomal dominant form of disease. "However, the precise mechanism by which mutations in LITAF cause an autosomal dominant disease has been the subject of debate." (PMID 33059769, 2020).
peripheral neuropathies (1 paper, 2020). "Our investigations have been conducted on fibroblasts, but it is the functional effects of LITAF and FIG4 mutations in Schwann cells that are likely to help explain the underlying pathomechanism of these inherited demyelinating peripheral neuropathies." (PMID 33059769, 2020).
LITAF also shares sentences with these, for which no sentence is quoted: breast carcinoma (3 papers); acute leukemia (2); acute myeloid leukemia (1); asthma (1); Charcot-Marie-Tooth disease type 1 (1); E. coli infection (1); extramammary Paget disease (1); hepatocellular carcinoma (1); inflammation (1); inflammatory bowel disease (1); Paget disease (1); pancreatic ductal adenocarcinoma (1); psoriasis (1); pulmonary fibrosis (1); ulcerative colitis (1).